CD24 (CD24 molecule)
Description:
May have a pivotal role in cell differentiation of different cell types. Signaling could be triggered by the binding of a lectin-like ligand to the CD24 carbohydrates, and transduced by the release of second messengers derived from the GPI-anchor. Modulates B-cell activation responses. Promotes AG-dependent proliferation of B-cells, and prevents their terminal differentiation into antibody-forming cells. In association with SIGLEC10 may be involved in the selective suppression of the immune response to danger-associated molecular patterns (DAMPs) such as HMGB1, HSP70 and HSP90. Plays a role in the control of autoimmunity (By similarity).
Synonyms: CD24A
Tractability: Antibody: UniProt places it where antibodies can reach, with medium confidence; UniProt predicts a signal peptide or a membrane-spanning region; its Gene Ontology location is reachable by antibodies, with medium confidence.
Gene: Protein-coding gene on chromosome 6 (106,969,831 to 106,975,627, reverse strand). Ensembl gene ENSG00000272398.
Subcellular location: Cell membrane
Subcellular location (Human Protein Atlas): Vesicles
Pathways (Reactome):
Developmental Biology: Developmental Lineage of Mammary Gland Alveolar Cells; Developmental Lineage of Mammary Gland Luminal Epithelial Cells; L1CAM interactions
Gene Ontology:
Molecular function: protein binding; protein kinase binding; protein tyrosine kinase activator activity; carbohydrate binding; Hsp70 protein binding; Hsp90 protein binding
Biological process: B cell receptor transport into membrane raft; cell activation; glomerular parietal epithelial cell differentiation; negative regulation of transforming growth factor beta3 production; podocyte differentiation; positive regulation of activated T cell proliferation; positive regulation of cytosolic calcium ion concentration; positive regulation of nephron tubule epithelial cell differentiation; regulation of MAPK cascade; respiratory burst; response to estrogen; response to hypoxia; T cell costimulation; cell migration; cell-cell adhesion; chemokine receptor transport out of membrane raft; cholesterol homeostasis; immune response-regulating cell surface receptor signaling pathway; intrinsic apoptotic signaling pathway; regulation of cell-cell adhesion; regulation of cytokine-mediated signaling pathway; regulation of epithelial cell differentiation; response to molecule of bacterial origin; Wnt signaling pathway; cell adhesion; and 5 more
Cellular component: cell surface; membrane; membrane raft; external side of plasma membrane; ciliary membrane; microvillus membrane; motile cilium; plasma membrane
Genetic constraint (gnomAD): Loss-of-function variants: 0 observed, 0.0866 expected, observed/expected ratio (o/e) 0, 90% interval 0 to 1.89. That is too few expected variants to judge how well the gene tolerates losing a copy. Missense variants: 47 observed, 49.75 expected, observed/expected ratio (o/e) 0.94, 90% interval 0.75 to 1.21. Synonymous variants: 19 observed, 19.91 expected, observed/expected ratio (o/e) 0.95, 90% interval 0.67 to 1.4.
Homologues: Orthologues: pig CD24 (78% identical), dog CD24 (76% identical), rat Cd24 (66% identical), mouse Cd24a (41% identical).
Diseases named in the same sentence as CD24 in open-access papers:
CD24 is named in the same sentence as 361 diseases in open-access papers, as found by Europe PMC text mining. Sharing a sentence is not in itself a finding about the gene and the disease. The quoted sentences say what the papers report.
breast cancer (903 papers, 2003 to 2026). A primary or metastatic malignant neoplasm involving the breast. "Next, we validated HER2 and CD24 as immunomagnetic targets for the specific isolation of breast cancer associated EV miRNA." (PMID 40405296, 2025). "Cytoplasmic spreading has also been previously seen in response to CD24 expression, which was associated with enhanced proliferation, invasion, and metastatic spread in breast cancer." (PMID 40754577, 2025). "First, proteomic analysis of EVs isolated in the HER2+ and CD24+ EV isolates would enable more precise comparison of the two subpopulations of breast cancer-associated EVs." (PMID 40405296, 2025). "The CD24+ expression in PDOs was linked to intra-tumor heterogeneity and high metastatic properties of breast cancer." (PMID 40821783, 2025). "Radiation resistance also appears closely linked to the presence of breast cancer stem-like cells marked by CD44(+)/CD24(−/low) expression." (PMID 40864743, 2025). "CD24, which is a regulator of cell migration, invasion, and proliferation in certain cancers, is often overexpressed in tumors and is a potential biomarker for breast cancers, as CD24 overexpression is associated with poor prognosis." (PMID 39513819, 2024). "In fact, EpCAM and CD24 are associated with HER2-positive breast cancer, which can be seen from their co-expression on cell lines." (PMID 39513819, 2024). "CD24lo/CD44hi (expressing high levels of CD44 and low levels of CD24) is a major hallmark of breast cancer stem cells." (PMID 38285090, 2024). "We identified CD38 on IgD+ CD24‐ as a mediator in the causal relationship between Species M funiformis and breast cancer." (PMID 39654239, 2024). "In cancer, CD24 is highly expressed in various tumor cells, including breast cancer cells, and associated with the growth, invasion, and migration of tumor cells." (PMID 37875600, 2023). "In summary, BEND3 is a significant gene highly associated with CD24 in breast cancer, and serves as a potential therapeutic target." (PMID 36882451, 2023). "MDA‐MB‐231 cells express high levels of the mesenchymal marker CD44 and intermediate levels of the epithelial marker CD24, a phenotype early on linked to high tumor‐initiating (or cancer stem cell) ability of patient‐derived breast cancer xenografts." (PMID 37518985, 2023). "In the current study, our target is to construct a CD24-associated ceRNA network, and to further identify key prognostic biomarkers in breast cancer." (PMID 36882451, 2023). "Our study provided clear evidence of significant CD24 up-regulation at the protein and mRNA levels in breast cancer, and it has been suggested to be a high-risk factor resulting in poor prognosis in patients with breast cancer." (PMID 37842046, 2023). "An additional subpopulation of CD44+/CD24+ cells of the BRCA1-mutated basal-A/basal-like breast cancer was sorted using an antibody against CD338 (ABCG2 antigen) and found to be enriched in several stemness markers." (PMID 36834918, 2023). "Triple-negative breast cancer (TNBC) displays the breast cancer stem cell (BCSC) phenotype of CD44+/CD24-, possesses tumor-initiating properties, and is associated with stem cell-like characteristics in breast cancer." (PMID 37736551, 2023). "Certain previous studies have reported that positive CD24 expression increases the metastatic potential of malignant cells and is associated with poor clinical outcomes in breast carcinomas." (PMID 37919766, 2023). "Further corroborating this CD24− BCSC phenotype, evidence from in vitro studies demonstrated that the overexpression of CD24 was associated with the inhibition of stem-like properties in breast cancer cells." (PMID 35326385, 2022). "Several markers have already been linked to certain types of CSCs (breast cancer: CD44+/CD24−/ALDH+; leukemia: CD34+/CD8−; liver: CD90+; pancreas: CD44+/CD24+/ESA+; epidermal surface antigen)." (PMID 35659296, 2022).
breast cancer (continued). "Stemness markers have been studied to identify BCSC, such as CD44/CD24 expression lines, which have shown a significant association with distant metastatic breast cancer subtypes for TNBCs." (PMID 36120232, 2022). "In ovarian and breast cancer, Siglec-10 is an inhibitory receptor expressed in tumor-associated macrophages (TAMs) that regulates immunity by interacting with CD24, suppressing immune responses, and promoting tumor progression." (PMID 35418152, 2022). "Meta-analysis with breast cancer tissues indicated that higher CD24 expression was associated with shorter OS and correlated with tumor stage and lymph node metastasis." (PMID 35037689, 2022). "The current study assessed the frequency of CD44-/CD24- breast cancer cells in 576 tissue specimens for associations with clinicopathological features and metastasis and investigated the underlying molecular mechanisms." (PMID 34318746, 2021). "More importantly, a higher frequency of CD44-/CD24- cells in breast cancer tissues was associated with significantly with worse DFS and delayed distant metastasis." (PMID 34318746, 2021). "Association of a high frequency of CD44-/CD24- cells in breast cancer tissues with delayed tumor distant metastasis." (PMID 34318746, 2021). "The results indicated that higher frequency (≥19.5%) of CD44-/CD24- cells was associated with delayed postoperative breast cancer metastasis." (PMID 34318746, 2021). "Strong CD24 expression was linked to a rapid tumor progression in epithelial ovarian cancer, breast cancer, non-small cell lung carcinoma, prostate cancer, and pancreatic cancer." (PMID 34360811, 2021). "The results from the current study indicated that patients with a higher frequency of CD44-/CD24- cells in their breast cancer tissues had a high risk to develop delayed distant metastasis 5–7 years after diagnosis." (PMID 34318746, 2021). "For example, fibroblasts secreting high levels of PGE2 had enhanced tumor growth and increased proportion of CD44+/CD24- cells, and the ability to secrete PGE2 was associated with the ability to expand CD44+/CD24- breast cancer cells in vivo." (PMID 35127497, 2021). "In a meta-analysis of 16 studies of 5697 breast cancers, CD24 was found to be significantly associated with poorer survival, presumably due to non EMP functions." (PMID 33276802, 2020). "On the other hand, CD24 is associated with carbohydrate metabolism and a more epithelial phenotype in breast cancer." (PMID 33102470, 2020). "CD44 is associated with a mesenchymal phenotype, while CD24 is associated with an epithelial phenotype in breast cancer." (PMID 33102470, 2020). "In contrast to the CD44+/CD24−/low phenotype, which is rather associated with basal-like breast cancer, ALDH1 positive cells were found in basal-like, luminal and HER2 breast cancers." (PMID 32430004, 2020). "For example, Zolkiewska and colleagues found that selumetinib blocked EGF-induced expansion of CD44+/CD24– breast cancer stem cell associated populations." (PMID 32391382, 2020). "The positive association between the CD44+/CD24-/low presence and AR expression was more obvious in ER+ breast cancers, which was consistent with our in vitro results." (PMID 29423076, 2018). "Clinically, CD24 overexpression is significantly associated with unfavorable outcomes in patients with luminal A breast cancers or with breast tumors of intermediate-grade differentiation." (PMID 29510720, 2018). "Although putative breast cancer stem cells have been suggested to express the CD44+/CD24- marker combination, CD24 alone has been implicated in the regulation of tumor growth and metastasis in previous studies." (PMID 29416796, 2018). "With sequence analysis, we suggest that let-7a (PAOM score 48.2) and miR-98a (PAOM score 12.0) are predicted to be strongly associated with CD24 in breast cancer." (PMID 30013305, 2018). "We confirmed that 8 genes—MAPK14, CLOCK, NF2, HMGA2, CXCL12, E2F1, NOTCH1, and CD24—are associated with breast cancer." (PMID 30013305, 2018).
breast cancer (continued). "As CD24 expression is often associated with CD44 expression in breast cancer cells, we analyzed CD44 cell surface expression in Mvt1-derived scrambled and ATF5-KD cells." (PMID 28785242, 2017). "Epithelial-mesenchymal transition is associated with CD44 high/CD24 low-expressing breast cancer stem and stem-like cells, and CD44 was part of the GSEA Hallmarks EMT gene set found enriched among the differentially expressed genes in DIP2C−/− cells." (PMID 28716088, 2017). "For example, in breast cancer the EMT state has been associated with cancer stem cell properties including the expression of stem cell-associated CD44+/CD24-/low antigenic profile, self-renewal capabilities and resistance to conventional therapies." (PMID 27102300, 2016). "In conclusion, our data demonstrated that high CD24 expression is significantly associated with poor survival in patients with early-stage breast cancer." (PMID 26444008, 2015). "On the contrary, truncated glioma-associated oncogene homolog 1 up-regulated CD24 gene expression in breast cancer cells, thereby contributing to enhanced migration and invasiveness in breast cancer cells." (PMID 26444008, 2015). "Breast cancer stem cells (BCSCs) with biomarker of ESA+CD44+CD24-/low have been reported as the origin of different pathological types of breast cancer and the radical cause of drug resistance, tumor relapse and metastasis in breast cancer." (PMID 26400441, 2015). "For identification of stem cell phenotype, many studies showed that high levels of CD44 associated to low levels of CD24 (CD44(+)/CD24(−/low)) would characterize stem populations in breast cancer." (PMID 26504780, 2015). "Our study revealed that high CD24 expression is correlated with the presence of LN metastasis and advanced pathological stage, suggesting that CD24 is associated with aggressive breast cancer." (PMID 26444008, 2015). "Consistent with previous studies, we found a significant association of high CD24 expression with worse clinical outcomes in the entire group of patients with breast cancer." (PMID 26444008, 2015). "Consistent with the induction of Snail1 and Twist, ectopic NKG2D–DAP10 expression (constitutive or Dox-induced) was associated with breast cancer stem cell-like CD24−/CD44+ profile shifts in the MCF-7–TF, MCF-10AT–TF and SUM149PT–TF lines." (PMID 25291178, 2014). "Expression of CD24 has been associated with breast cancer cells of low tumorigenic capacity, and several studies demonstrate that expression of CD24 can classify functionally distinct subpopulations of tumor cells." (PMID 25419568, 2014). "The CD44 high/CD24 low phenotype in breast cancer cell has been linked to EMT through the mesenchymal attributes of breast cancer stem cells, which also have dramatically enhanced malignant properties." (PMID 26237148, 2013). "The association between CD24 and P-selectin was confirmed due to the interaction of mammary cancer cells and P-selectin in activated platelets." (PMID 23419168, 2013). "A CSC gene signature from comparative analysis of CD44+CD24− sorted tumor cells and cancer mammospheres showed that this signature was associated with claudin-low breast cancers, suggesting that claudin-low tumors are enriched for CSCs." (PMID 23986719, 2013). "High levels of CD44 associated to low levels of CD24 (CD44(+)/CD24(-/low)) would characterize stem populations in breast cancer." (PMID 23976904, 2013). "Controversial reports on the association of a CD44(+) CD24(-/low) phenotype and poor prognosis of breast cancer have been reported." (PMID 24392029, 2013). "Based on gene expression profiles, basal-like breast cancers have been associated with the surface marker expression CD44+/CD24-/low while luminal epithelial cells have been associated with CD24+/CD44- expression." (PMID 24229464, 2013).
breast cancer (continued). "Noteably, CD44(+)/CD24(-/low) breast cancer stem-like cells are associated with tumor recurrence and play a pivotal role in the clinical behavior of triple-negative breast cancer, a particularly therapy-resistant subclass of breast cancer." (PMID 24392029, 2013). "CD24 has previously been implicated in breast cancer, for example as a marker for the breast cancer-initiating cell population." (PMID 23785296, 2013). "Another study using flow cytometry showed that 6.1% of the lymph node metastases contained CD44+/CD24- cells and found an association between metastatic dissemination and increased numbers of cells with this phenotype in human mammary neoplasms." (PMID 24119896, 2013). "CD24-/lowCD44+ breast CSCs have been suggested to be the underlying cause of breast cancer recurrence and are a critical target for breast cancer therapies." (PMID 23662114, 2013). "The combined expressions with CD44 associated with stem cell-like characteristics and CD24 related to differentiated epithelial features as prognostic markers for breast cancer however remains controversial." (PMID 23046710, 2012). "Although CD44+/CD24- cells are believed to act as breast cancer stem cells and to be linked to poor prognosis in some patients, the association between these cells and tumor recurrence or metastasis in all or some types of invasive ductal carcinoma is unclear." (PMID 22762532, 2012). "Several studies have shown an association between CD44+/CD24- cells and the metastasis of basal-like breast cancers." (PMID 22762532, 2012). "In univariate analysis, CD44+CD24-/low expression showed association with death due to breast cancer (p = 0.035)." (PMID 21824412, 2011). "Presence of CD44+/CD24- tumor cells has also been associated with the aggressive basal-like molecular subtype of breast cancer." (PMID 21957977, 2011). "We demonstrated that breast cancer cells with CD44+/CD24- phenotype express elevated levels of invasion-associated genes and are invasive but this phenotype is not a requisite for homing and growth at sites of metastasis." (PMID 20691079, 2010). "Using either CD44+/CD24- or CD133+ cells isolated from Brca1-deficient mouse mammary tumors, expression of Sox1 was found to be significantly higher in these cells when compared to their counterparts." (PMID 20929579, 2010). "Thy1, a marker of myoepithelial and fibroblastic cells, has been linked to mammary CSCs, as a small subset of Thy1+/CD24+ cells, comprising 1%–4% of the tumor cells purified from mammary carcinomas in MMTV-Wnt-1 mice, has been found to behave like CSCs." (PMID 20730114, 2010). "Second, some Brca1-deficient tumors contain CD44+/CD24-/Low cells, previously associated with human breast cancer stem cells, whereas others contain CD133+ cells previously associated with tumors in other organs." (PMID 18241344, 2008). "We found that CD44+/CD24- Brca1-deficient mouse mammary tumor cells have cancer stem cell characteristics in vitro, and 50 of these cells are sufficient to initiate tumors in mice." (PMID 18241344, 2008). "Recently, CD44+CD24-/low lineage-cells were implicated in breast cancer initiated tumorigenesis in NOD/SCID mice." (PMID 18433506, 2008). "Finally, we discovered that “CD38 on IgD+ CD24‐” served as a mediator in the causal relationship between Species M funiformis and breast cancer, with a mediating ratio of 11.20%." (PMID 39654239, 2024). "We chose cancer markers CD24 and EpCAM due to their association with breast cancer." (PMID 39513819, 2024). "In addition, a study indicated that CD44(+)/CD24(−/low) breast cancer stem-like cells play a pivotal role associated with the clinical behavior of triple-negative breast cancer." (PMID 38392969, 2024). "CD24 expression is also closely associated with poor prognosis in patients with breast cancer." (PMID 37894750, 2023).